CLDN3 (claudin 3)
Diseases named in the same sentence as CLDN3 in open-access papers (continued):
Sharing a sentence is not in itself a finding about the gene and the disease.
breast carcinoma (continued). "Claudin-3 was detected in the nucleus of breast cancer cell lines and colorectal adenocarcinomas." (PMID 38338705, 2024). "Breast cancer (BCa) is the most common malignancy in women and claudin-low breast cancer (CL-BCa) is a newly identified BCa subtype characterized by low expression of claudin 3&4&7." (PMID 35359417, 2022). "Such apparent mislocalizations were also described for the CLDN-3 protein in human breast cancer derived cell lines and may be related to local invasiveness." (PMID 27690019, 2016). "However, recent studies have shown that the distinct prognostic significance of claudin-3 or claudin-4 is dependent on the subtype of breast cancer." (PMID 24009024, 2013). "A fusion toxin in which the protein synthesis inhibitory factor (PSIF) was attached to a C-terminal fragment of CPE (C-CPE) was capable of inducing cytolysis in CLDN3/4-expressing MCF-7 human breast cancer cells implying that C-CPE-PSIF must have entered the cytosol." (PMID 21303546, 2011). "CLDN3 positivity was most seen in neuroendocrine neoplasms (92–100%) and in adenocarcinomas (67–100%), tumors of the female genital tract, including various subtypes of ovarian and endometrial carcinoma (up to 100%), as well as different subtypes of breast cancer (95.3–100%)." (PMID 39658782, 2024). "In addition, CLDN3 expression was also having versatility in breast carcinoma." (PMID 28160565, 2017). "Breast cancer cell lines reflective of the CL subtype were also found to express low or absent levels of the epithelial cell-cell adhesion proteins examined (E-cadherin, claudin 3, claudin 4 and claudin 7) and markers of breast luminal epithelial cell differentiation (ER, PR and HER-2)." (PMID 28045912, 2017). "Specific examples include increased expression of claudin-3 and -4 in types of prostate and uterine cancer, high claudin-4 expression in pancreatic cancer, downregulation of claudin-7 in head and neck and metastatic breast cancer, and an increase in claudin-3 and -4 in breast cancer." (PMID 25120725, 2014). "For example, CLDN1, CLDN3, CLDN7, CLDN16 and CLDN20 have been found to be downregulated in breast cancer, and the downregulation of these claudins appearing to be linked to a more aggressive phenotype and with poor clinical outcome." (PMID 38137355, 2023). "Recent studies reported that drug-resistant breast cancer cells acquire EMT characteristics and have increased motility and invasion activities by suppression of CLDN3, CDH1, and PTPRK." (PMID 35335125, 2022). "It has been reported that recovery of various claudin proteins expression, such as CLDN3, CLDN4, and CLDN7, can reduce the malignant behavior of cancer cells and reduce the invasiveness in breast cancer." (PMID 29221203, 2017). "Previous studies have elaborated the expression of CLDN3 and CLDN4 effect on the metastatic ability of breast cancer cells." (PMID 29221203, 2017). "For example, the range of reported CLDN3 positive cases ranged from 25 to 73.6% in gastric cancer, from 32 to 95% in breast cancer of no special type, and from 41.4 to 97.0% in pulmonary adenocarcinoma." (PMID 39658782, 2024). "In contrast, CLDN3, CLDN4 and CLDN5 appear to be overexpressed in breast cancers." (PMID 38137355, 2023). "Triple-negative breast cancers have been sub-classified into specific molecular subtypes that include basal-like breast cancers (CK5/6-positive and/or EGFR-positive) and claudin-low breast cancers exhibiting low expression of the CDH1 and claudin 3, 4 and 7 genes." (PMID 26988558, 2016). "Instead, a claudin-low intrinsic subtype of breast cancer has been described as a subset of basal-like breast cancers characterized by low to absent expression of claudin 3 and E-cadherin (CDH1), as well as stem-cell like features." (PMID 26556851, 2015). "The previously discovered role of claudin-3 and claudin-4 in cell motility and increased MMP-2 activity suggests that this may be yet another metastasis-promoting molecule in breast carcinoma effusions." (PMID 19680458, 2010).
breast carcinoma (continued). "In addition, low levels of claudin-3, -4, and -7 is a hallmark of a subgroup of mainly triple-negative (no amplification of HER2 and negative for estrogen and progesterone receptors) breast cancers with mesenchymal and cancer stem cell-like features." (PMID 26083392, 2015). "Both RJ348 and RJ423 cells expressed only extremely low levels of Cldn3, Cldn4 and Cldn7 (data not shown) suggesting that both RJ348 and RJ423 cells share features of human claudin-low breast cancers." (PMID 28423599, 2017). "Using this approach we determined that claudin-low breast cancer is typically negative for ER, PR, HER2, claudin 3, claudin 4, claudin 7 and E-cadherin." (PMID 28045912, 2017). "In addition, both parental bipotent and MPCs do not express proteins such as, claudin 3, ER, ESA, MUC1 and GATA3, that are known signature of claudin-low breast cancers." (PMID 22514728, 2012).
colitis (33 papers, 2011 to 2026). Inflammation of the colon. "In the same the way, claudin-3 knockout mice showed an enhanced susceptibility to DSS-induced colitis and to dysbiosis." (PMID 40723233, 2025). "Among class 1 Cldns, deficiencies in Cldn3 to 7, 11, and 18.1 have been linked to cancers, colitis, infertility, respiratory infections, neurological disorders, and other disorders, as demonstrated largely by KO mouse studies." (PMID 41171911, 2025). "Overall, these data affirmed the causal role of CLDN3 in maintaining normal gut homeostasis, and that the loss of CLDN3 promotes colitis." (PMID 38010872, 2023). "In the current study, we show that CLDN3 expression is downregulated to its nadir in IBD patients and murine models of colitis, and the loss of CLDN3 expression promotes the development of colitis and disease severity." (PMID 38010872, 2023). "Having demonstrated that the loss of CLDN3 expression in the mouse gut promotes gut dysbiosis and that these mice have an increased susceptibility to colitis, we further examined the relevance of CLDN3 expression in IBD and associated microbiome changes." (PMID 38010872, 2023). "In summary, our data suggest that CLDN3 loss of expression promotes activation of key proinflammatory cytokines and signaling pathways during colitis." (PMID 38010872, 2023). "Further analysis using IBD patient cohorts and murine models of colitis provides additional evidence for the causal role of CLDN3 loss in promoting IBD." (PMID 38010872, 2023). "We found that DSS-induced colitis was associated with decreased expression of colonic claudin-1, claudin-3, claudon-5, claudin-7 and claudin-8, and also increased expression of colonic claudin-2." (PMID 22073304, 2011). "The causal role was determined by modeling CLDN3 loss of expression during experimental colitis." (PMID 38010872, 2023). "Treatment with Voclosporin led to a significant increase of the barrier-strengthening protein claudin 3 in the colon of mice with experimentally induced colitis." (PMID 41704697, 2026). "In a previous study, L. gasseri JM1 showed the effect of alleviating the damaged barrier structure by increasing the expression of claudin-3, occludin, and ZO-1 and regulating inflammatory and anti-inflammatory cytokines in a mouse model of colitis." (PMID 40002326, 2025). "In a study, CLA production enhanced by Bifidobacterium longum CCFM681 ameliorated DSS-associated colitis by increasing MUC2, claudin-3, α-catenin 1, and ZO-1 (goblet cells involved in the protection of the intestinal mechanical barrier)." (PMID 40806004, 2025). "Mulberry anthocyanins alleviated colonic tissue damage and the inflammatory reaction in DSS-induced colitis mice and maintained the intestinal barrier by restoring the levels of intestinal tight junction (TJ) proteins (claudin-3, occludin, and ZO-1)." (PMID 39947703, 2025). "We found a similar downregulation of CLDN3 expression in the colons of mice subjected C. rodentium colitis." (PMID 38010872, 2023). "We further show that the gut microbiome in Cldn3KO mice plays a major role in sensitivity to colitis, emphasizing the therapeutic significance of CLDN3 in promoting intestinal barrier maturity/integrity as well as maintaining normal gut microbiota." (PMID 38010872, 2023). "A significant decrease in CLDN3 expression characterized IBD and CLDN3 loss of expression promoted colitis." (PMID 38010872, 2023). "The total protein level of claudin-3 in proximal colon was unaltered during DSS-colitis compared to control mice." (PMID 34445403, 2021). "An upregulation of pore-forming claudin-2 and downregulation of sealing claudin-3 has been reported in ulcerative colitis, as well as in experimental colitis models, leading to altered TJ structure and barrier dysfunction." (PMID 34445403, 2021). "First, our study confirmed that EFEL6901 increased E-cadherin and claudin-3 levels, and that these changes in tight junction protein expression were considered a major factor in colitis relief." (PMID 34899643, 2021).
colitis (continued). "It was also reported that that expression of OCLN and CLDN3 is reduced in DSS-induced colitis compared to the control group." (PMID 34444876, 2021). "VIP protects the distribution and levels of junction proteins (for example, ZO-1, occludin, claudin-3, and claudin-4) against colitis by inhibiting MLCK or PKCε." (PMID 34552687, 2021). "Additional induction of colitis evoked a downregulation of claudin-3 in both intestinal segments and an upregulation of claudin-4 in the jejunum." (PMID 30971956, 2019). "In another study, naringenin ameliorated DSS-induced colitis by restoring the expression of tight junction proteins such as occludin, junctional adhesion molecule-A, and claudin-3." (PMID 27635116, 2016). "In colitis group, immunostaining of claudin-2 was increased in intensity, whereas the intensity of claudin-3 immunostaining was decreased." (PMID 22073304, 2011). "Treated with CXCR4 antagonist AMD3100 significantly promoted colonic claudin-1, claudin-3, claudin-5, claudin-7 and claudin-8 expressions, and also decreased colonic claudin-2 in colitis mice." (PMID 22073304, 2011). "The expressions of colonic claudin-1, claudin-3, claudin-5, claudin-7 and claudin-8 in colitis mice were markedly decreased as compared with control mice." (PMID 22073304, 2011). "Furthermore, claudin-3 knockout sensitizes mice to experimental colitis, induced by DSS and by C. rodentium, enhances the proinflammatory cytokine level and promotes dysbiosis." (PMID 40723233, 2025). "Interestingly, upon colitis induction by DSS or C. rodentium infection, the loss of CLDN3 expression significantly exacerbated the expression of TNF-α and IL-6." (PMID 38010872, 2023). "We next examined status of CLDN3 expression in a murine model of colitis." (PMID 38010872, 2023). "We also found that mouse P2Y1R deficiency in mice significantly reduced goblet cell loss and intestinal permeability; increased the levels of tight junction proteins occludin, claudin-3, and ZO-1; and decreased claudin-2 in the colon tissues of mice with colitis." (PMID 37781034, 2023). "Therefore, it is particularly crucial to determine the effect of L. gasseri JM1 on the mRNA expressions of intestinal tight junction proteins (Claudin-2, Claudin-3, Occludin and ZO-1) in mice with colitis." (PMID 36615796, 2022). "In DSS-induced colitis in mice, intestinal permeability increased significantly, and tight-junction proteins occludin, claudin 1 and claudin 3 that are closely related to intestinal permeability decreased, whereas RJ significantly improved the changes of intestinal permeability." (PMID 35631210, 2022). "When in addition to the sensitization a colitis was induced, a significant decrease in claudin-3 immunofluorescence was observed in both intestinal segments, whereas the immunofluorescence for claudin-4 was unchanged in the colon, but increased significantly in the jejunum." (PMID 30971956, 2019). "Moreover, in the present study, we found that treated with CXCR4 antagonist AMD3100 significantly promoted colonic claudin-1, claudin-3, claudin-5, claudin-7 and claudin-8 expressions, and also decreased colonic claudin-2 in colitis mice." (PMID 22073304, 2011). "A decreased accumulation of both claudin-3 transcripts and proteins has been evidenced in colonic samples from patients with IBD and from animal models of colitis." (PMID 40723233, 2025). "Overall, our data established that CLDN3 expression was sharply downregulated in IBD and murine models of colitis." (PMID 38010872, 2023). "After treatment with SC-5, the expression levels of occludin, claudin-3, and ZO-1 were up-regulated compared with the DSS group (p < 0.05), indicating that SC-5 can alleviate DSS-induced colitis in mice by enhancing the expression of tight junction proteins." (PMID 36832972, 2023).
colitis (continued). "Tight junction proteins such as E-cadherin, occludin, and claudin-3 are involved in barrier function in the intestine, and their low expression levels are closely related with DSS-induced colitis." (PMID 34899643, 2021). "Using a Salmonella-colitis mouse model and cultured colonic epithelial cells, we found that pathogenic Salmonella colonization significantly increases the levels of claudin-2 protein and mRNA in the intestine, but not that of claudin-3 or claudin-7 in the colon, in a time-dependent manner." (PMID 23505542, 2013). "Our present study also demonstrated that AMD3100 increased the expression of colonic claudin-1, claudin-3, claudon-5, claudin-7 and claudin-8, decreased of colonic claudin-2 expression in DSS-induced colitis." (PMID 22073304, 2011). "Using both of these approaches, we observed consistently no change in the expression of the claudin-3 isoform in the test conditions, suggesting that it has no role in the development of the acute stage of colitis in the present model." (PMID 39334888, 2024). "Expression of Cldn3, Cldn4, Cldn7 and Cdh1 mRNA was however not altered during colitis or due to the absence of Muc13 expression in mice." (PMID 37174625, 2023). "In addition, the administration of loganin and morroniside as the physiological components of C. fructus prevented epithelial barrier injury by increasing the expression of Muc2, ZO-1, claudin-3, occludin, and E-cadherin in DSS-induced colitis." (PMID 36613533, 2022). "In mice model of colitis, resveratrol, diet with red raspberries powder (rich in insoluble fiber), and dietary CLA (conjugated linolenic acid) administration upregulated tight junction proteins E-cadherin 1, ZO-1, CLDN3 and OCCL gene expressions." (PMID 33806347, 2021). "However, claudin-3 expression in distal colon was significantly decreased by DSS colitis (p = 0.031 vs. DSS), which was not apparent after FI5pp treatment." (PMID 34445403, 2021). "Another research group found that the expression of both OCLN and CLDN3 is reduced and that CLDN1 is not affected in DSS-induced colitis compared to the control group." (PMID 32370215, 2020).
prostate carcinoma (22 papers, 2011 to 2026). A carcinoma that arises from epithelial cells of the prostate gland. "To analyze the possible role of CLDN3 in the progression of prostate cancer, we analyzed the effect of CLDN3 loss of expression on the cell phenotype." (PMID 36614243, 2023). "Given its high expression in the majority of cases of prostate cancer, and the fact that it has been implicated as a possible therapeutic target, claudin-3 warrants additional studies to evaluate its potential as a clinically useful biomarker in the diagnosis of prostate cancer." (PMID 21255442, 2011). "In our study, the loss of CLDN3 expression observed in CRPC cells and tumors could be explained, at least in part, by the loss of CLDN3 control by AR, since it has been demonstrated that AR regulates a different expression profile in androgen-sensitive and independent prostate cancer cells." (PMID 36614243, 2023). "On the other hand, a meta-analysis of the use of CLDN-3 for the evaluation of prostate cancer showed that CLDN3 is indeed one of the strongest two markers overexpressed in cancer when compared with prostate-specific antigen." (PMID 38731853, 2024). "In prostate cancer, CLDN3 expression has been found in normal, PIN, primary and metastatic prostate cancer." (PMID 36614243, 2023). "Comparing the DNA methylation and expression profile of androgen-sensitive and -refractory prostate cancer cells, we describe the epigenetic silencing of claudin-3 (CLDN3) in AR positive cells resistant to androgen deprivation (LNCaP-abl)." (PMID 36614243, 2023). "Analyzing clinical follow up yielded CLDN3 loss of expression implied a lower disease-free survival and time to clinical progression, indicating that CLDN3 expression can predict the prognosis of prostate cancer patients." (PMID 36614243, 2023). "Claudin 3- andclaudin 4-expressing prostatic cancer cells have been shown to be strikingly sensitive to CPE-mediated cytolysis." (PMID 36714681, 2023). "Previously, we found that Cldn3 and Cldn4 are expressed in aggressive high-grade human prostate cancer specimens." (PMID 35006480, 2021). "Although Cldn3 and Cldn4 have been shown to be expressed in prostate cancers, and was the focus of CPE intervention, targeting Cldn3 and Cldn4 expression in relation to prostate cancer cell survival rates has not been investigated." (PMID 35006480, 2021). "Herein, we showed that knocking down Cldn3 or Cldn4 expression in prostate cancer cells decreased cell survival." (PMID 35006480, 2021). "It is well documented that CPE receptors CLDN-3, -4, and/or -7 are abnormally regulated in many tumor types including prostate cancer, which also was confirmed for the used 0840 and 0846 cell lines." (PMID 34830170, 2021). "Knocking down Cldn3 and Cldn4 expression appears to be androgen independent as both human prostate cancer cell lines PC3 (androgen independent) and LNCaP (androgen dependent) had similar growth outcomes." (PMID 35006480, 2021). "The goal of our study was to examine the differences in Cldn3 and Cldn4 protein levels according to growth characteristics of prostate cancer cells." (PMID 35006480, 2021). "We and others have shown that there are higher levels of Cldn3 and Cldn4 in metastatic human prostate cancer cells than in normal human prostate cells." (PMID 35006480, 2021). "Herein, we target Cldn3 and Cldn4 expression in prostate cancer cells using Cldn3 and Cldn4 siRNAs and assess its impact on cell growth, migration, viability, and clonogenic survival." (PMID 35006480, 2021). "The expression of Cldn3 and Cldn4 is tissue specific and has been described to be up-regulated in ovarian, breast, and prostate cancers." (PMID 35006480, 2021). "Cldn3/Cldn4 siRNA treatment resulted in a greater than 85% decrease in the protein levels of Cldn3 and Cldn4, which was accompanied by a 30–40% decrease in prostate cancer cell growth and a 60–65% reduction in cell viability." (PMID 35006480, 2021).